HMOX1 (heme oxygenase 1)
Diseases named in the same sentence as HMOX1 in open-access papers (continued):
Sharing a sentence is not in itself a finding about the gene and the disease.
hypertriglyceridemia (2 papers, 2012 to 2015). A laboratory test result indicating elevated triglyceride concentration in the blood. "Our data suggest that polymorphisms of HMOX1 and NQO1 genes are associated with a high risk of metabolic disorders, including high systolic and diastolic blood pressure, hypertriglyceridemia, and low HDL-c levels in Mexican Mestizo individuals." (PMID 25933176, 2015). "The present study provides additional evidence that polymorphisms of the HMOX1 and NQO1 genes are associated with high risk in metabolic disorders, such as blood systolic and diastolic pressure, hypertriglyceridemia, and low levels of HDL-c." (PMID 25933176, 2015).
intestinal infection (2 papers, 2018 to 2024). "Furthermore, intestinal infections are an important factor in the development of IBD and most of the evidence available to date supports the notion that HMOX1 promotes bacterial clearance, diminishing intestinal inflammation." (PMID 30258436, 2018).
keratoconus (2 papers, 2020 to 2024). A degenerative, structural disorder of the eye, characterized by a cone-shaped protrusion of the cornea. "HMOX1 is an important NRF2-downstream antioxidant target gene that catabolizes heme and resolves iron imbalance and toxicity, and decrease in its transcript in both keratoconus patient groups affirms NRF2 dysfunctions." (PMID 32555404, 2020).
leprosy (2 papers, 2020 to 2022). Leprosy is a chronic infectious disease affecting primarily the skin and peripheral nervous system. "Leprosy household contacts had decreased soluble CD163 and heme oxygenase 1 (HO-1) serum levels when compared with healthy donors and leprosy patients." (PMID 35552484, 2022). "Although IDO and HMOX1 have been described as associated with immunosuppression in leprosy multibacilary patients, we did not observe a significant correlation between these two markers when comparing leprosy non-co-infected patients (BT and RR groups)." (PMID 32849508, 2020).
Lewis lung carcinoma (2 papers, 2022 to 2024). "In this regard, a previous study on immunogenic Lewis lung carcinoma cells identified FAP+CD45+ cells as a subset of F4/80hiCCR2+CD206+ M2 macrophages and the main tumoral source of the immune inhibitory enzyme heme oxygenase-1 (HO-1)." (PMID 36263225, 2022).
macrophage activation syndrome (2 papers, 2020 to 2022). A complication of rheumatic disease that is caused by excessive activation and uncontrolled proliferation of T lymphocytes and well-differentiated macrophages. "HMOX1-deficiency is a rare autosomal recessive disorder with hallmark features of direct antibody negative hemolytic anemia with normal bilirubin, hyperinflammation and features similar to macrophage activation syndrome." (PMID 33066778, 2020).
meningioma (2 papers, 2017 to 2020). A generally slow growing tumor attached to the dura mater. "In particular, the mRNA expression level of Hmox1 was significantly increased, and this effect was counteracted when TS-PDT was combined with ZnPPIX, reducing meningioma cell viability." (PMID 32455831, 2020).
muscle atrophy (2 papers, 2022 to 2025). The loss of muscle tissue due to inactivity or disease. "Regarding neurogenic muscle atrophy, quercetin suppresses TNF-α-induced C2C12 myotube atrophy by interfering with the activation of NF-κB and the consequent activation of the ubiquitin ligases atrogin-1 and MuRF-1, and by activating the Heme Oxygenase 1 (HO-1)." (PMID 36422289, 2022).
muscular atrophy (2 papers, 2020 to 2025). "Previous studies have shown that HMOX1 is an anti-inflammatory and antioxidant enzyme that can promote myofibroblast differentiation by inhibiting muscle injury, and its expression is reduced in muscular atrophy." (PMID 40756204, 2025).
ocular hypertension (2 papers, 2013 to 2017). Abnormally high intraocular pressure. "Ocular hypertension caused upregulation of heme oxygenase-1—an hypoxia-inducible and redox-sensitive enzyme—in ONH astrocytes." (PMID 28883787, 2017).
oral mucositis (2 papers, 2020 to 2024). Inflammation of the mucous membranes of any of the structures in the mouth. "Treatment of oral mucositis with AuNp (250 μg/kg) increased the gene expression of the antioxidant enzyme, hemeoxygenase 1 (HMOX-1), in relation to 5-FU animals (p < 0.0001 vs. 5-FU)." (PMID 32230975, 2020).
pancreatic adenocarcinoma (2 papers, 2024). "We explored the expression of several antioxidants (NRF2, GPX2, SOD1,2) and NRF2 target genes (NQO1, HMOX1, TXN) in 179 tumors and 171 normal tissues from the TCGA/GTEx pancreatic adenocarcinoma (PAAD) dataset." (PMID 38782891, 2024). "Analyzing data publicly available in KMplot, both NFE2L2 and HMOX1 expression are significantly (p = 4.16 × 10−48 and p = 7.81 × 10−54, respectively) upregulated in pancreatic adenocarcinomas compared with non-cancerous pancreatic tissue." (PMID 39337472, 2024). "Additionally, low expression levels of HMOX1 and NFE2L2 correlate with extended survival in patients with pancreatic adenocarcinoma." (PMID 39337472, 2024).
Pressure Ulcers (2 papers, 2018 to 2022). "Therefore, the presence of HMOX1 gene polymorphisms might identify persons at high risk for low collagen density, which is a risk for pressure ulcers and skin tears." (PMID 30024897, 2018). "Thus, the examination of HMOX1 gene polymorphisms might identify persons at high risk for low collagen density, which is a risk for pressure ulcers and skin tears caused by external forces in obese patients." (PMID 30024897, 2018).
progeria (2 papers, 2019 to 2022). "Stress response pathways reflecting oxidative stress/inflammation and DNA damage responses are activated in mouse models of progeria, with the induction of Hmox1 being an early event." (PMID 36201626, 2022). "To test this hypothesis, we generated novel accelerated ageing (progeria) reporter mice by crossing the LmnaG609G mice into our oxidative stress/inflammation (Hmox1) and DNA damage (p21) stress reporter models." (PMID 36201626, 2022).
prostate adenocarcinoma (2 papers, 2020 to 2022). "In addition, tumors with lymph node and/or distant metastasis had significantly higher HMOX1 expression than tumors without metastasis, including prostate adenocarcinoma (PRAD) and LUAD." (PMID 36033490, 2022).
pulpitis (2 papers, 2023 to 2024). Inflammation of the dental pulp. "Amongst the 22 modules, the darkgray module was determined as the most pivotal module for pulpitis, from which 5 core genes, A HMOX1, LOX, ACTG1, STAT3 and GNB5, were selected, and assumed to exert pivotal effects on the pathophysiologic causal links of pulpitis." (PMID 36593446, 2023). "Subsequently, the protein coding genes HMOX1, LOX, ACTG1, STAT3, GNB5 were selected as the core genes, as they were most negatively or positively correlated modules with pulpitis statistically." (PMID 36593446, 2023). "However, to our knowledge, HMOX1 has not been studied in pulpitis yet." (PMID 36593446, 2023).
scleroderma (2 papers, 2011 to 2021). Scleroderma is a rare autoimmune connective tissue disorder characterized by abnormal hardening of the skin and, sometimes, other organs. "Curcumin treatment increased apoptosis in scleroderma lung fibroblast (SLF) but not in normal lung fibroblast (NLF), because protein kinase C (PKC) and heme oxygenase 1 (HO-1) and glutathione-S-transferase P1 (GST P1) are not active in SLF." (PMID 34258301, 2021).
septic shock (2 papers, 2023 to 2025). Shock caused by infection; frequently caused by gram negative bacteria, although some cases have been caused by other bacteria, viruses, fungi, and protozoa; characterized by fever, chills, tachycardia, tachypnea, and hypotension. "In patients with septic shock, calcitriol increased the expression of IL-10 (2.6-fold, adjusted P < 0.05), whereas in those without septic shock, calcitriol increased the expression of HMOX1 (1.3-fold, adjusted P < 0.05)." (PMID 40924491, 2025).
small-intestinal adenocarcinoma (2 papers, 2018 to 2025). "It has been demonstrated that HMOX1 is highly expressed in CRC and high expression of HMOX1 in small-intestine adenocarcinomas is associated with lower pT (primary tumor) category, less pancreatic invasion and longer overall survival than those with low HMOX1 expression." (PMID 30258436, 2018).
temporal lobe epilepsy (2 papers, 2023 to 2024). A localization-related (focal) form of epilepsy characterized by recurrent seizures that arise from foci within the temporal lobe, most commonly from its mesial aspect. "Upregulation of leukocyte NCF2, RAC2 and HMOX1 expression in this study is predictive of low temporal lobe epilepsy seizure frequency, while downregulation of these genes predicts high seizure frequency." (PMID 38166692, 2024). "NCF2, RAC2 and HMOX1 activity all promote epileptogenicity through mitochondrial oxidative stress, neuronal lipid peroxidation, and neuronal and glial toxicity, all of which are consistent with the redox imbalance hypothesis of temporal lobe epilepsy." (PMID 38166692, 2024).
transient cerebral ischemia (2 papers, 2011 to 2024). "At the same time, transcriptional upregulation of heme oxygenase-1 in RVLM by hypoxia-inducible factor-1α (HIF-1α) plays a pro-life role in experimental brain death, and HIF-1α is subject to sumoylation activated by transient cerebral ischemia." (PMID 21390240, 2011).
alcoholic liver cirrhosis (1 paper, 2012). A disorder of the liver characterized by the presence of fibrotic scar tissue instead of healthy liver tissue. "Rare variants identified by sequencing of HMOX1 in alcoholic chronic pancreatitis (ACP), idiopathic/hereditary chronic pancreatitis (ICP/HP), and alcoholic liver cirrhosis (ALC) patients and controls and their location within HMOX1." (PMID 22666428, 2012).
allergic reactions (1 paper, 2024). "IgE-mediated allergic reactions can trigger Nrf2 activation, leading to the expression of Heme-oxygenase-1 (HO-1), a protective antioxidant enzyme." (PMID 38790633, 2024).
avascular necrosis (1 paper, 2022). Necrotic changes in the bone tissue due to interruption of blood supply. "This study detected five target genes (IL-1β, STAT3, CAT, PTGS2, and HMOX1) to further study the effects of quercetin, luteolin, kaempferol, cryptotanshinone, and naringenin on the expression of related genes in steroid-induced avascular necrosis of the femoral head." (PMID 35915795, 2022).
childhood asthma (1 paper, 2025). "Discuss the correlation between single nucleotide polymorphisms (SNPs) of the Glutathione s-transferase Pi-1 (GSTP1), Catalase (CAT), Heme oxygenase-1 (HMOX1), and Homo sapiens epoxide hydrolase 1 (EPHX1) genes and the risk of childhood asthma in Fuzhou." (PMID 40433469, 2025). "Association analysis results showed that SNPs at GSTP1 gene rs1695, rs4891, HMOX1 gene rs17878790, CAT gene rs7943316, and rs769217 loci are associated with the risk of childhood asthma in Fuzhou region." (PMID 40433469, 2025). "To date, there is no research on the association between GSTP1, CAT, HMOX1, EPHX1 gene SNPs and the risk of childhood asthma in the Fuzhou region." (PMID 40433469, 2025).
chronic hepatitis B (1 paper, 2019). "Associations of miR-122 expressed in liver and anti-oxidant genes, such as heme oxygenase 1 (HMOX-1), NAD(P)H, quinone oxidoreductase-1 (NQO1), and growth factor erv1-like (GFER1) in liver tissue specimens obtained from patients with chronic hepatitis B, have been uncovered." (PMID 31640265, 2019).
diffuse large B-cell lymphoma (1 paper, 2017). "Heme oxygenase-1 (HO-1) can promote tumor growth and reinforce the resistance of diffuse large B-cell lymphoma (DLBCL) cells to chemotherapeutic drug vincristine." (PMID 29108243, 2017).
filariasis (1 paper, 2021). "TLR-mediated expression of Cyclooxygenase-2 (Cox-2), Heme Oxygenase-1 (HO-1), and Indoleamine-2,3-Dioxygenase (IDO) constitute a immunoregulatory circuit, which controls filariasis-mediated immunomodulation." (PMID 34566972, 2021).
Friedreich ataxia (1 paper, 2024). An inherited condition that affects the nervous system and causes movement problems. "The second phase, spanning 2017 to 2020, explores keywords such as ‘amyloid precursor protein, HD, neurofibrillary tangles, antioxidant, peroxidation, inactivation, cell death mechanisms, metabolism, toxicity, heme oxygenase 1, Friedreich’s ataxia,’ emphasizing the impact of ferroptosis on ND." (PMID 38962561, 2024).
Fulminant hepatitis (1 paper, 2022). Acute hepatitis complicated by acute liver failure with hepatic encephalopathy occurring less than 8 weeks after the onset of jaundice. "It has been reported to ameliorate concanavalin-A-induced mouse experimental fulminant hepatitis and increased heme oxygenase-1 (HO-1) expression through mitogen-activated protein kinase/nuclear factor erythroid 2-related 2 (MAPK/Nrf2) antioxidant pathway in RAW264 macrophage cell lines." (PMID 35243333, 2022).
hemoglobinopathies (1 paper, 2013). "How do hemoglobinopathies impact the resting endogenous levels of angiopoietin-1, angiopoietin-2, and heme oxygenase-1?" (PMID 23696730, 2013).
Hemophagocytosis (1 paper, 2020). Phagocytosis by macrophages of erythrocytes, leukocytes, platelets, and their precursors in bone marrow and other tissues. "The boy reported herein is a case of HMOX1 deficiency notable for the presence of chronic pulmonary disease and inflammatory flares with notable hemophagocytosis." (PMID 33066778, 2020).
Hodgkins lymphoma (1 paper, 2023). A heterogeneous group of malignant lymphoid neoplasms of B-cell origin characterized histologically by the presence of Hodgkin and Reed-Sternberg (HRS) cells in the vast majority of cases. "Indeed, it was recently reported that HIF‐regulated HMOX1 contributes to the maintenance of the undifferentiated phenotype in the SP of Hodgkin lymphoma." (PMID 36775962, 2023).
Hypoglycemia (1 paper, 2020). A decreased concentration of glucose in the blood. "The reduced late insulin response in Hmox1-/- mice could be induced by insulin antagonistic pathways in response to hypoglycemia such as hepatic gluconeogenesis, alterations in the hypothalamic–pituitary–adrenal axis and increased inflammatory cytokines." (PMID 32992485, 2020).
hypopharyngeal cancer (1 paper, 2023). Carcinoma, predominantly squamous cell, arising from the epithelial cells of the hypopharynx. "In summary, we confirmed that HOXC-AS2 can affect the expression of HMOX1 by regulating the NF-KB signaling pathway, thus regulating autophagy and the progression of hypopharyngeal cancer." (PMID 37944249, 2023). "Our results confirmed that HOXC-AS2 can affect the expression of HMOX1 by regulating the NF-KB signaling pathway, thus regulating autophagy and the progression of hypopharyngeal cancer." (PMID 37944249, 2023). "HOXC-AS2 and P62 expression was significantly upregulated in hypopharyngeal cancer tissues compared with normal hypopharyngeal tissues, while HMOX1 expression was decreased." (PMID 37944249, 2023). "It was confirmed that HOXC-AS2 can bind to the P62 protein and activate the NF-KB signaling pathway, thereby affecting HMOX1 expression and regulating autophagy in hypopharyngeal cancer cells, ultimately regulating the formation and progression of hypopharyngeal cancer." (PMID 37944249, 2023). "In conclusion, HOXC-AS2 can bind to the p62 protein to activate the NF-KB signaling pathway, thereby regulating the expression of HMOX1 and ultimately affecting autophagy in hypopharyngeal cancer cells to facilitate the formation and progression of hypopharyngeal cancer." (PMID 37944249, 2023).
intracranial hypertension (1 paper, 2020). A finding characterized by increased cerebrospinal fluid pressure within the skull. "This increased heme oxygenase-1 level can be considered a defense mechanism of choroid plexus cells against oxidative stress triggered by intracranial hypertension." (PMID 33328892, 2020).
liver neoplasm (1 paper, 2024). Tumors or cancers of the LIVER.
melasma (1 paper, 2023). "Our findings revealed decreased levels of NRF2, heme oxygenase-1, IFT88, and GLIs in lesional skin from melasma patients." (PMID 38001823, 2023).
minimal change disease (1 paper, 2022). "SAA combined with prednisone exhibited therapeutic and antiproteinuric effects on adriamycin-induced minimal change disease rat model through PPARγ/Angptl4 and Nrf2/Heme oxygenase-1 (HO-1) pathways." (PMID 35528835, 2022).
nosocomial infection (1 paper, 2015). An infection acquired in a hospital or other healthcare setting. "The remaining transcriptomic candidates of the heme degradation pathway (HP, CD163, HMOX1; IL-10) and IL-8 clustered together, with moderate correlation to nosocomial infections (lower half of the heatmap)." (PMID 26607226, 2015).
pancreatic NET (1 paper, 2025). "Data from previous studies suggest that HMOX1 might play different roles in many cancer pathways, including that the longer promoter GTn repeat polymorphism of HMOX1 is associated with worse prognosis in pancreatic NET patients." (PMID 40998421, 2025).
parotid tumor (1 paper, 2021). "In qRT-PCR, mRNA expression levels of Sod2, heme oxygenase 1 (Ho-1) and glutathione reductase (Gr) were higher in the PMA type of parotid tumor tissue in comparison to healthy tissue." (PMID 34360635, 2021).
perinatal disease (1 paper, 2021). A condition affecting an unborn or newly born individual, where the perinatal period is defined in humans as commencing at 22 completed weeks (154 days) of gestation and ending seven completed days after birth. "The contribution of HMOX1 promoter polymorphisms to human diseases has been studied since the 1990s; however, evidence regarding perinatal disease is still insufficient." (PMID 33805292, 2021). "Thus, this article aimed to systematically review published evidence of the associations between HMOX1 polymorphisms and the development of perinatal diseases and summarize them." (PMID 33805292, 2021). "We systematically reviewed published evidence on HMOX1 polymorphisms in perinatal diseases and clarified their possible significant contribution to neonatal jaundice development, presumably due to their direct effect of inducing HO enzymatic activity in the bilirubin-producing pathway." (PMID 33805292, 2021). "As its contribution to the development of perinatal complications is speculated, two functional polymorphisms of the HMOX1 gene, (GT)n repeat polymorphism (rs3074372) and A(-413)T single nucleotide polymorphism (SNP) (rs2071746), were studied for their association with perinatal diseases." (PMID 33805292, 2021).
pertussis (1 paper, 2025). A contagious bacterial respiratory infection caused by Bordetella pertussis. "Using the DGIdb database, we identified potential drug candidates for three biomarkers: HMOX1 (9 drugs, with Stannsoporfin achieving the highest score), TLR4 (22 drugs, with the pertussis vaccine scoring the highest), and ACE (59 drugs, with cilazapril scoring the highest)." (PMID 40282274, 2025).
prediabetes (1 paper, 2020). "Heme oxygenase-1, the key enzyme for synthesizing bilirubin, may be upregulated to deal with oxidative stress during the stages of prediabetes and new-onset diabetes, and leading to an increase in the downstream product bilirubin so as to play antioxidant effects." (PMID 32802055, 2020).
pregnancy toxemia (1 paper, 2025). "PCR-DNA sequence analysis revealed that the amplified fragments of IL-6 (627 bp), IL-8 (264 bp), FASN (381 bp), SOD3 (393 bp), HMOX1 (460 bp), and ACACA (477 bp) differed between healthy goats and those affected by pregnancy toxemia (PT)." (PMID 41012815, 2025).